RNU6-1169P (RNA, U6 small nuclear 1169, pseudogene)
Gene: Small nuclear RNA gene on chromosome 15 (41,448,742 to 41,448,844, reverse strand). Ensembl gene ENSG00000200407.
Homologues: Orthologues: chimpanzee U6 (98% identical), macaque U6 (86% identical), rabbit U6 (79% identical), rabbit U6 (73% identical). Paralogues in human: RNU6-116P (92% identical), RNU6-41P (92% identical), RNU6-1060P (90% identical), RNU6-10P (90% identical), RNU6-1124P (90% identical), RNU6-12P (90% identical), RNU6-13P (90% identical), RNU6-25P (90% identical), RNU6-32P (90% identical), RNU6-338P (90% identical), RNU6-33P (90% identical), RNU6-44P (90% identical), and 1287 more.